WNT7A (Wnt family member 7A)
Diseases named in the same sentence as WNT7A in open-access papers (continued):
Sharing a sentence is not in itself a finding about the gene and the disease.
lymph node metastasis (4 papers, 2012 to 2021). "Univariate Cox regression analysis suggested that WNT7A expression, tumor differentiation as well as lymph node metastasis associated with poor prognosis." (PMID 30361522, 2018). "The expression of WNT7A was higher in EC tissue than in normal endometrial tissue, and increased WNT7A expression has been associated with a high tumor grade and stage, increased depth of myometrial invasion, vascular/lymphatic invasion, lymph node metastasis and worse prognosis in EC." (PMID 31287002, 2019). "High expression of WNT7A significantly correlated with N classification (p = 0.033), which suggested a potential link between WNT7A and lymph node metastasis." (PMID 30361522, 2018). "Furthermore, we noticed that high expression of WNT7A significantly positive correlated with lymph node metastasis in TMA, which insight the potential link between the WNT7A and tumor metastasis." (PMID 30361522, 2018). "Wnt7a was inversely correlated with FIGO stage (P = 0.001), grade (P = 0.001), lymph node metastasis (P = 0.002), depth of myometrial invasion (P = 0.006), lymph vascular space involvement (P = 0.001) and peritoneal cytology (P = 0.013)." (PMID 23304155, 2012). "The positive expression of Wnt7a protein was not related to the gender, age, lesion location, path length, depth of invasion, and distant metastasis (P > 0.05), but was related to the TNM stage, cell differentiation, and lymph node metastasis." (PMID 33791195, 2021).
lung adenocarcinoma (3 papers, 2013 to 2019). A carcinoma that arises from the lung and is characterized by the presence of malignant glandular epithelial cells. "During the pulmonary aging process Wnt4 and Wnt5a were identified as inhibitors of lipid uptake and therefore surfactant production, while Wnt7a triggered differentiation and reduced proliferation of lung adenocarcinoma cell lines, respectively." (PMID 31492143, 2019). "miRNA expression profiling on a human lung adenocarcinoma cell line (A549) identified hsa-miR29b as an important downstream target of Wnt7a/Frizzled9 signaling." (PMID 23862015, 2013). "Additionally, recent study revealed that DAPK2, MFSD2A, THSD1 and WNT7A were oncogenes which showed high expression and low methylation in lung adenocarcinoma." (PMID 30899432, 2019). "As a strategy to identify potential miRNAs involved in the Wnt7a-dependent regulation of NSCLC cell growth, we performed miRNA expression profiling on Wnt7a-stimulated human lung adenocarcinoma cell line (A549) and identified hsa-miR29b as an important downstream target of Wnt7a." (PMID 23862015, 2013). "To identify potential miRNAs involved in Wnt7a-dependent regulation of NSCLC cell growth, we performed miRNA expression profiling of human lung adenocarcinoma cell line A549 as described in Materials and Methods." (PMID 23862015, 2013).
osteoarthritis (3 papers, 2017 to 2019). A noninflammatory degenerative joint disease occurring chiefly in older persons, characterized by degeneration of the articular cartilage, hypertrophy of bone at the margins and changes in the synovial membrane. "Down-regulation of Wnt7a in human osteoarthritis cartilage and an inverse correlation between Wnt7a levels and catabolic gene expression in human articular chondrocytes in vitro has been reported." (PMID 31546898, 2019).
ovarian tumor (3 papers, 2012 to 2019). "We have recently reported that aberrant WNT7A is observed in serous ovarian carcinomas, and WNT7A is the sole ligand accelerating ovarian tumor progression through CTNNB1 (β-catenin)/TCF signaling in the absence of CTNNB1 mutations." (PMID 27195958, 2016).
acute myeloid leukemia (2 papers, 2012 to 2022). Acute myeloid leukemia (AML) is a group of neoplasms arising from precursor cells committed to the myeloid cell-line differentiation. "Peripheral blood cells from four Acute myeloid leukemias (AML), three Chronic myeloid leukemia (CML), and five Chronic lymphocytic leukemia (CLL) also revealed a tendency to exhibit reduced WNT7A expression when compared with the control group (data not shown)." (PMID 22313908, 2012).
Amelia (2 papers, 2020 to 2025). Congenital absence (aplasia) of one or more limbs. "To date, TBX5 has been associated with upper amelia, TBX4 with lower amelia, and WNT3, WNT7A and RSPO2 with tetra-amelia syndromes in humans (and cattle, for RSPO2)." (PMID 40131457, 2025).
breast tumor (2 papers, 2016 to 2019). "Previously it was shown that secreted Wnt7A by breast tumor cells causes fibroblasts to assume an activated phenotype based on their expression of alpha smooth muscle actin (αSMA)." (PMID 31443683, 2019). "Using in vivo models we identify Wnt7a as a key factor secreted exclusively by aggressive breast tumour cells, which induces CAF conversion." (PMID 26777421, 2016).
clear cell renal cell carcinoma (2 papers, 2012 to 2019). "For instance, it has been demonstrated that Wnt7a expression was reduced owning to the methylation in clear cell renal cell carcinoma." (PMID 31886205, 2019). "For this purpose, the expression of the WNT7A gene in 17 clear cell renal cell carcinomas was determined by qRT-PCR." (PMID 23056560, 2012). "In the present work hypermethylation of the WNT7A gene was detected in 66% (29/44) of analyzed clear cell renal cell carcinomas (RCCs) using methyl-specific PCR (MSP)." (PMID 23056560, 2012).
colon cancer (2 papers, 2020 to 2021). "Then, sphere formation experiment and plate clone formation experiment were carried out in vitro to verify the effect of Wnt7a on the growth of colon cancer cells." (PMID 33791195, 2021). "Clonal formation assay was used to detect the effect of knockdown Wnt7a on colonization ability of colon cancer cells." (PMID 33791195, 2021). "In addition, to investigate the potential role of Wnt7a in colon cancer tumorigenesis, Wnt7a was silenced in the colon cancer cell lines HT29 and HT116." (PMID 33791195, 2021). "In this study, siRNAs specific to Wnt7A were transfected into 2 colon cancer cell lines." (PMID 33791195, 2021). "After knockdown of Wnt7A, the number of clone formation of HT-29 and HCT 116 of colon cancer cells was significantly reduced compared with the control group." (PMID 33791195, 2021). "By studying colon cancer pathologic specimens, we confirmed that DYDC2, MS4A15, MAGEA1, WNT7A, APOD, and SERPINE1 were highly expressed in colon cancer tissues." (PMID 33680915, 2020).
depression (2 papers, 2015 to 2026). "Collectively, this study found that CUMS-induced depression is associated with a significant upregulation of hippocampal Wnt7a, β-catenin, and GSK-3β, along with increased GSK-3β phosphorylation." (PMID 41732723, 2026). "Here, we report that Wfs1, a gene that can cause depression, is co-expressed with Ntf3, Penk, and Wnt7a in supragranular 2/3 pyramidal neurons in the mPFC." (PMID 26371510, 2015). "Hippocampal Wnt7a and β-catenin expression levels were analyzed to investigate their mechanistic involvement in depression." (PMID 41732723, 2026).
diabetes (2 papers, 2020 to 2021). "Similarly, dietary supplementation with resveratrol enhances the expression of hippocampal Wnt7a and neurogenesis of diabetic mice, indicating a potential neuroprotective role of Wnt7a in diabetes." (PMID 34042263, 2021).
head and neck squamous cell carcinoma (2 papers, 2018 to 2024). A squamous cell carcinoma that arises from any of the following anatomic sites: lip and oral cavity, nasal cavity, paranasal sinuses, pharynx, larynx, and salivary glands. "WNT7A, a member of the Wnt family, remains poorly understood in terms of its role and the underlying molecular mechanisms it entails in head and neck squamous cell carcinoma (HNSCC)." (PMID 38246919, 2024). "DACT, WNT5A, and WNT7B were significantly positive correlation with TET1(p < 0.05), and WNT4 and WNT7A were negative correlation with TET1 in the TCGA Head and Neck Squamous cell Carcinoma database (p < 0.05)." (PMID 30075814, 2018).
leiomyoma (2 papers, 2012 to 2015). A well-circumscribed benign smooth muscle neoplasm characterized by the presence of spindle cells with cigar-shaped nuclei, interlacing fascicles, and a whorled pattern. "These previous results indicate that decreased Wnt7a expression is associated with the development of sex-hormone-dependent endometrial carcinoma and leiomyoma." (PMID 23304155, 2012). "Decreased Wnt7A expression may lead to loss of control in the patterning of the myometrium and result in the development of leiomyoma." (PMID 25632963, 2015). "Hypersensitivity of leiomyoma cells to estrogen may deregulate Wnt7A expression." (PMID 25632963, 2015).
melanoma (2 papers, 2022 to 2024). A malignant, usually aggressive tumor composed of atypical, neoplastic melanocytes. "There are even more Wnt ligands, such as Wnt2 and Wnt7a, that have been described to have tumor suppressive effects on different cancer types and on melanoma cells (Wnt2)." (PMID 38388496, 2024). "Among them, WNT3 and WNT4 were implied as melanoma tumor suppressors; WNT7A and WNT10A displayed contribution to the female reproductive system adenocarcinomas." (PMID 35850748, 2022).
microcephaly (2 papers, 2018 to 2025). A congenital or acquired developmental disorder in which the circumference of the head is smaller than normal for the person's age and sex. "Knockout of Wnt7a in mice causes microcephaly due to reduced NP population and neurogenesis, and Sfrp1 has an opposing effect compared to Wnt7a." (PMID 30065628, 2018). "Decreased expansion of cortical NPs is likely a major cause of microcephaly in Wnt7a KO mice." (PMID 30065628, 2018). "Knockout of Wnt7a causes microcephaly due to reduced numbers of NPs and decreased neurogenesis." (PMID 30065628, 2018). "Moreover, we have shown that the deletion of Wnt7a expression causes microcephaly by reducing the population of NPs and newborn neurons." (PMID 30065628, 2018).
muscular dystrophy (2 papers, 2015 to 2021). Muscular dystrophy (MD) refers to a group of more than 30 genetic diseases characterized by progressive weakness and degeneration of the skeletal muscles that control movement. "It has been also reported that Wnt7a treatment ameliorates muscular dystrophy, reducing the level of contractile damage and significantly increasing muscle strength of mdx mice." (PMID 26137572, 2015). "Moreover, Wnt7a delays the muscular dystrophy progression by stimulating SCs expansion in mdx mice." (PMID 34347392, 2021).
osteoporosis (2 papers, 2019 to 2021). A condition of reduced bone mass, with decreased cortical thickness and a decrease in the number and size of the trabeculae of cancellous bone (but normal chemical composition), resulting in increased fracture incidence. "Quantitative real-time PCR shown that Wnt1, Wnt5a, Wnt7a, and Wnt9a mRNAs were lower expressed in osteoporosis derived EVs." (PMID 34375951, 2021). "In this study, the expression and correlation of miR-889 and WNT7A was determined by osteoporosis patients and healthy controls." (PMID 31727100, 2019). "Osteoporosis patients and normal control bone tissues were collected and used PCR techniques to identify the change of miR-889 and WNT7A." (PMID 31727100, 2019). "In addition, the results of our study demonstrated that the mRNA levels of Wnt1, Wnt5a, Wnt7a, and Wnt9a were lower in osteoporosis-derived EVs than in non-osteoporosis-derived EVs, while DKK mRNA was up-regulated in osteoporotic individuals compared to non-osteoporotic individuals." (PMID 34375951, 2021). "Quantitative real-time PCR shown that Wnt1, Wnt5a, Wnt7a, and Wnt9a mRNAs were lower expressed in osteoporosis derived EVs, while DKK mRNA was up regulated in osteoporosis compared to non-osteoporotic individuals." (PMID 34375951, 2021).
pancreatic ductal adenocarcinoma (2 papers, 2018 to 2019). An infiltrating adenocarcinoma that arises from the epithelial cells of the pancreas. "And the role of WNT7A in Pancreatic ductal adenocarcinoma remains unclear." (PMID 30361522, 2018).
Parkinson disease (2 papers, 2014 to 2018). A progressive degenerative disorder of the central nervous system characterized by loss of dopamine producing neurons in the substantia nigra and the presence of Lewy bodies in the substantia nigra and locus coeruleus. "Agreeing with the role of alpha-synuclein at presynapses, several genes annotated for the Gene Ontology-slim term synapse showed differential expression, some of them previously associated with Parkinson's disease including Nptx2, Wnt7a, and Rims3." (PMID 29755323, 2018). "In future research, we will evaluate the effects of combining Wnt7a with Shh and FGF to provide a possible translational application for Parkinson's disease." (PMID 25170755, 2014).
pulmonary hypertension (2 papers, 2023 to 2025). Increased pressure within the pulmonary circulation due to lung or heart disorder. "It has been shown that RvE1, acting through the ChemR23 receptor, can attenuate experimental pulmonary hypertension in mice by inhibiting Wnt family member 7A (Wnt7a)/β-catenin signaling." (PMID 40559469, 2025).
acute lymphoblastic leukemia (1 paper, 2012). Leukemia with an acute onset, characterized by the presence of lymphoblasts in the bone marrow and the peripheral blood. "With this aim, the expression of WNT7A was analyzed in 14 samples of patients with Acute lymphoblastic leukemia (ALL) and in 19 samples of clinically healthy volunteers." (PMID 22313908, 2012).
adenocarcinoma of the ovary (1 paper, 2009). "OVCAR-3, a cell line derived from ascites of a patient with adenocarcinoma of the ovary, showed low expression of WNT7A, and was considered a good candidate for over-expression." (PMID 19849863, 2009).
alcohol (1 paper, 2022). "Moreover, induction of alcohol-induced liver disease in rats resulted in increased expression of cytosolic and nuclear β-catenin, phosphorylated GSK3β, and significantly increased gene expression of Wnt2, Wnt7a, and β-catenin target genes." (PMID 35663960, 2022).
Alzheimer disease (1 paper, 2014). A progressive, neurodegenerative disease characterized by loss of function and death of nerve cells in several areas of the brain leading to loss of cognitive function such as memory and language. "Thus, combining Wnt7a with RB and sAPPα in hMSCs may enable cholinergic neurons to be generated more efficiently, providing a potential therapy for Alzheimer's disease." (PMID 25170755, 2014).
angioleiomyoma (1 paper, 2018). A benign, slow-growing neoplasm that arises from the dermis or subcutaneous tissue. "Only six genes show significant differences between the angioleiomyoma types (ISL1, NCSTN, TCF7, WNT10A, WNT11, WNT7A) but their relative expression levels were very low, which indicates no biological relevance (< 0.4 compared to standardized reference gene index)." (PMID 29881541, 2018).
aortic valve disease (1 paper, 2022). "In addition, we analyzed the protein localization of Sox9 and Aggrecan (key proteins implicated in the pathogenesis of aortic valve disease), as well as Wnt7a and Opg (which showed altered expression in RNASeq) using immunohistochemistry." (PMID 36005436, 2022).
astrocytoma (1 paper, 2020). "Moreover, WNT7A was also showed lower expressed in astrocytoma than in NB tissues." (PMID 32181818, 2020).
attention deficit-hyperactivity disorder (1 paper, 2024). A disorder characterized by a marked pattern of inattention and/or hyperactivity-impulsivity that is inconsistent with developmental level and clearly interferes with functioning in at least two settings (e.g. at home and at school). "Impairment in the Wnt pathway has been associated with various psychiatric disorders in humans, such as WNT1, WNT2, and WNT7A in autism spectrum disorder, WNT7B and LRP5 in SCZ, and LRP5 and LRP6 in attention-deficit/hyperactivity disorder." (PMID 39452096, 2024).
clubfoot (1 paper, 2018). The most common congenital deformation of the foot, occurring in 1 of 1,000 live births. "They genotyped the CAND2 gene in 256 clubfoot patients and 75 control patients, while Wnt7a was screened using 56 clubfoot patients and 50 control patients." (PMID 30134936, 2018).
coeliac disease (1 paper, 2008). "While up-regulation of Wnt7A expression may provide a differentiation signal to epithelial cells, signalling via Wnt7a has also been shown to induce transcription of matrix metallproteinase 12 (MMP-12), an enzyme that has been implicated in coeliac disease pathophysiology." (PMID 18691394, 2008).
colon adenocarcinoma (1 paper, 2021). "The conclusion of this study suggests that the positive expression of Wnt7a in colon adenocarcinoma is significantly higher than that in colorectal adenoma and normal colorectal mucosa." (PMID 33791195, 2021).
colorectal adenocarcinoma (1 paper, 2021). The most common type of colorectal carcinoma. "The positive expression rate of Wnt7a in colorectal adenocarcinoma was significantly higher than that in colorectal adenoma and normal colorectal mucosa (P<0.01)." (PMID 33791195, 2021). "Wnt7a promotes the occurrence and development of colorectal adenocarcinoma." (PMID 33791195, 2021).
degenerative myopia (1 paper, 2025). "During the pathogenesis of degenerative myopia, WNT7A has been shown to regulate the plasticity of human retinal pigment epithelial cells, functionally associated with degenerative myopia." (PMID 40110040, 2025).
invasive breast carcinoma (1 paper, 2016). A carcinoma that infiltrates the breast parenchyma. "Immunohistochemical staining of an initial set of 65 human invasive breast cancers revealed an increased CAF activation in tumours with high Wnt7a expression." (PMID 26777421, 2016).
laryngeal carcinoma (1 paper, 2020). Carcinoma that arises from the laryngeal epithelium. "We first examined the protein levels of the key molecular markers, including cyclin D1, Wnt4, MYC, Wnt7A, and Wnt9A, of the Wnt/β-catenin signaling pathway in laryngeal carcinoma cells." (PMID 33060569, 2020).
leukoplakia (1 paper, 2007). A white patch or plaque on a mucous membrane that cannot be characterized clinically or pathologically as any other disease. "No signal was detectable with antibodies against Wnt1 and Wnt7a in normal and leukoplakia epithelia, whereas Wnt5a signal was ubiquitously detectable in normal oral epithelium, leukoplakia, and in OSCC (data not shown)." (PMID 17922924, 2007).
liver cancer (1 paper, 2019). An epithelial or non-epithelial malignant neoplasm that arises from the liver. "We first localized the Wnt7a levels using immunohistochemistry across 33 patient-derived liver cancer tissues." (PMID 31886205, 2019). "Taken together, all these observations show that Wnt7a inhibits growth and promotes apoptosis in liver cancer cells." (PMID 31886205, 2019). "In our study, we found that Wnt7a was underexpressed in 21 liver cancer tissues, out of 33 cases in total." (PMID 31886205, 2019).
lung diseases (1 paper, 2012). "Restoration of Wnt7a expression may also have potential application in other epithelial cancers or lung diseases." (PMID 22403725, 2012).
medulloblastoma (1 paper, 2010). A malignant, invasive embryonal neoplasm arising from the cerebellum. "In comparison, the genes Wnt3 and Wnt7a, which were found to be up-regulated by gene expression microarray analysis, were validated as up-regulated by real-time, RT-PCR and western blotting in SmoA1 +; Pten +/− medulloblastomas." (PMID 20520772, 2010).
mesothelioma (1 paper, 2015). A usually malignant and aggressive neoplasm of the mesothelium which is often associated with exposure to asbestos. "The mean level of Wnt7A expression had a significant correlation with International Mesothelioma Interest Group (IMIG) stage (P<0.034), gender, smoking history and ethnicity, respectively (P=0.020, P=0.014, P=0.039)." (PMID 25632963, 2015).
metastatic disease (1 paper, 2025). "WNT7A can upregulate expression of the cell adhesion-related protein fibronectin, which could contribute to the inhibition of cell adhesion in metastatic disease." (PMID 39858031, 2025).